FOXP1 (forkhead box P1)
Diseases named in the same sentence as FOXP1 in open-access papers (continued):
Sharing a sentence is not in itself a finding about the gene and the disease.
bladder cancer (4 papers, 2015 to 2025). "This experiment submits that further investigation into mechanisms underlying β-AR-mediated STAT3 regulation by Foxp1 will cast new light upon the Warburg effect of therapeutic strategies for bladder cancer." (PMID 37663229, 2023). "According to our results, Foxp1 mRNA expression level in paracancerous tissue was lower than that of I–II patients with bladder cancer, and Foxp1 mRNA expression of I–II patients with bladder cancer was lower than that of III–IV patients with bladder cancer." (PMID 37663229, 2023). "Downregulation of Foxp1 reduced glucose consumption, lactate production, and ATP quantity of bladder cancer cells." (PMID 37663229, 2023). "OS and DFS of Foxp1 low expression in patients with bladder cancer were higher than those of Foxp1 high expression." (PMID 37663229, 2023). "As a result, OS and DFS of Foxp1 low expression in patients with bladder cancer were higher than those of Foxp1 high expression." (PMID 37663229, 2023). "The study determined the role of β-AR controlling the effects of Foxp1 on cell growth and the Warburg effect of bladder cancer." (PMID 37663229, 2023). "In this study, we examined Foxp1 mRNA and protein expression levels in patients with bladder cancer were increased, compared with paracancerous tissue." (PMID 37663229, 2023). "In conclusion, Foxp1 promoted occurrence and development of bladder cancer through the Warburg effect by the activation of STAT3 activity and repressing β-AR transcription." (PMID 37663229, 2023). "Foxp1 mRNA and protein expression levels in patients with bladder cancer were increased, compared with paracancerous tissue (normal)." (PMID 37663229, 2023). "This study provided a new mechanism for understanding the Foxp1-indicated novel target for bladder cancer treatment." (PMID 37663229, 2023). "Here, this investigated the biological roles of Foxp1 in the occurrence and development of bladder cancer." (PMID 37663229, 2023). "It was found that Foxp1 plasmid increased the expression of Foxp1 mRNA level in bladder cancer cell." (PMID 37663229, 2023). "Foxp1 mRNA and protein expression levels in patients with bladder cancer were increasing, compared with paracancerous tissue (normal)." (PMID 37663229, 2023). "Surprisingly, we also observed Foxp1 promoted cell growth and increased Warburg effect in vitro model of bladder cancer." (PMID 37663229, 2023). "Expectedly, Foxp1 promoted STAT3 activity to heighten the Warburg effect by β-AR in a model of bladder cancer." (PMID 37663229, 2023). "Over-expression of Foxp1 promoted cell growth of bladder cancer cells, and down-regulation of Foxp1 reduced cell growth of bladder cancer cell." (PMID 37663229, 2023). "Here, we investigate the biological roles of Foxp1 in the occurrence and development of bladder cancer." (PMID 37663229, 2023). "Over-expression of Foxp1 promoted glucose consumption, lactate production, and ATP quantity in bladder cancer cells." (PMID 37663229, 2023). "Foxp1 has been found to bind to the upstream region of the β-adrenergic receptor (β-AR) promoter, inhibiting its expression, controlling brown/beige adipocyte differentiation, and promoting the progression of bladder cancer." (PMID 39143228, 2025). "As a next step in investigating the function of Foxp1 on the Warburg effect of bladder cancer." (PMID 37663229, 2023). "It is found that FOXP1 is abnormally expressed in various tumors such as breast cancer, lung cancer, bladder cancer, and lymphoma, which may become a tumor marker for clinical practice." (PMID 37663229, 2023). "Foxp1 is potential target to be used in the treatment of bladder cancer." (PMID 37663229, 2023). "In general, data suggest that β-AR is one important targets of Foxp1 in bladder cancer." (PMID 37663229, 2023). "We suggest that Foxp1 played a repair factor in bladder cancer cell growth." (PMID 37663229, 2023). "Thereafter, we examined the function of Foxp1 on cell growth of bladder cancer cell lines." (PMID 37663229, 2023).
bladder cancer (continued). "Of note, β-AR it is possible that the effects of Foxp1 may be the promoter factor for bladder cancer progress." (PMID 37663229, 2023). "Taken together, our data suggest that Foxp1 played a repair factor in bladder cancer." (PMID 37663229, 2023). "This work first examines the Foxp1 expression levels in patients with bladder cancer." (PMID 37663229, 2023). "Subsequently, to observe any potential mechanism of Foxp1 in bladder cancer, we examined gene expression levels by Foxp1 using microarray analysis and β-AR expression may be one important target for Foxp1 on cell growth of bladder cancer." (PMID 37663229, 2023). "Foxp1 mRNA expression level in GES-1 cells was lower than those of bladder cancer cell lines." (PMID 37663229, 2023). "Next, this work investigated the mechanism of Foxp1/β-AR on the Warburg effect of bladder cancer." (PMID 37663229, 2023). "Therefore, we focused Foxp1-promoted cell growth and migration rate of bladder cancer." (PMID 37663229, 2023). "β-AR inhibitor also reversed the effects of si-Foxp1 on glucose consumption, lactate production, ATP quantity, ECAR, and OCR relative levels in bladder cancer cells." (PMID 37663229, 2023). "Over-expression of Foxp1 promoted the migration rate and number of EDU cells in bladder cancer cells." (PMID 37663229, 2023). "Down-regulation of Foxp1 reduced the migration rate and number of EDU cells in bladder cancer cells." (PMID 37663229, 2023). "β-AR plasmid reversed the effects of Foxp1 on glucose consumption, lactate production, ATP quantity, ECAR, and OCR relative levels in bladder cancer cells." (PMID 37663229, 2023). "Down-regulation of Foxp1 reduced ECAR and OCR-relative levels of bladder cancer cells." (PMID 37663229, 2023). "Furthermore, over-expression of Foxp1 promoted extracellular acidification rate (ECAR) and OCR relative level of bladder cancer cells." (PMID 37663229, 2023). "The mRNA of β-AR was a negative correlation with serum Foxp1 levels in patients with bladder cancer." (PMID 37663229, 2023). "Taken together, our findings reveal that Foxp1 promoted the occurrence and development of bladder cancer through the Warburg effect by the activation of STAT3 activity and repressing β-AR transcription, and which might serve as an important clue for its targeting and treatment of bladder cancer." (PMID 37663229, 2023).
colorectal cancer (4 papers, 2015 to 2025). A primary or metastatic malignant neoplasm that affects the colon or rectum. "This study reveals a phosphorylation‐dependent mechanism involving AURKA and highlights the FBXO44/FOXP1/Cyclin E2 axis as a potential therapeutic target in colorectal cancer." (PMID 41051444, 2025). "We further explored the functional significance of FBXO44‐mediated FOXP1 regulation on the phenotype of colorectal cancer." (PMID 41051444, 2025). "FBXO44 promotes colorectal cancer progression by targeting FOXP1 for ubiquitin‐mediated degradation." (PMID 41051444, 2025). "Research in colorectal cancer has revealed that overexpression of circFoxp1 significantly increases the methylation level of the Foxp1 promoter, while knockout of circFoxp1 notably reduces this methylation." (PMID 39606233, 2024). "Furthermore, our study elucidates the mechanism by which phosphorylation and ubiquitination regulate FOXP1 degradation to promote colorectal cancer progression." (PMID 41051444, 2025).
COVID-19 (4 papers, 2022 to 2025). A disease caused by infection with severe acute respiratory syndrome coronavirus 2. "Among these, the expression levels of FOXK2, FOXO3, and FOXP1 were found lower in the lungs of COVID-19 patients, compared to controls, thus showing the same expression levels and trends as observed for ATP2B1 (Fig. EV1G,H)." (PMID 38816514, 2024). "From 11 healthy cell-type TRNs and 8 COVID-19 cell-type TRNs, we identified 8 unique central TFs, FOXP1, RUNX1, FOS, SMAD3, JUN, NFKB1, PPARG, and STAT3." (PMID 35458567, 2022). "The fourth set of modules involved ribosomal proteins and inflammasome function (top genes by membership included NLRP1, MAP3K14, and FOXP1) and was negatively correlated with COVID-19 severity in monocytes." (PMID 35216673, 2022).
glioblastoma (4 papers, 2015 to 2019). The most malignant astrocytic tumor (WHO grade IV). "In another report, Gomez GG found the EGFR mutation-induced miR-9 suppression could elevate glioblastoma tumorigenicity by activating FOXP1." (PMID 30795814, 2019). "For example, suppression of miRNA-9 by mutant EGFR signaling resulted in up-regulation of FOXP1 and enhanced glioblastoma tumorigenicity." (PMID 28060761, 2017). "In glioblastoma with epidermal growth factor receptor amplification, silencing FOXP1 expression inhibited epidermal growth factor receptor-dependent tumorigenicity." (PMID 26654944, 2016).
heart failure (4 papers, 2016 to 2026). Inability of the heart to pump blood at an adequate rate to meet tissue metabolic requirements. "Enhanced endothelial cell-FoxP1 function protects against pathological cardiac remodeling and improves cardiac insufficiency." (PMID 36088337, 2022). "According to reports, FOXP1 suppressed the TGF-β signaling pathway to prevent cardiac fibrosis and pathological remodeling during heart failure." (PMID 41596522, 2026). "Moreover, knockdown of FOXP1 in EC has been reported to induce fibrosis and myocardial remodeling via the upregulation of the expression of TGF-β, and ultimately lead to heart failure." (PMID 37084237, 2023).
liver cancer (4 papers, 2020 to 2023). An epithelial or non-epithelial malignant neoplasm that arises from the liver. "Compared to primary liver cancer, FOXP1 had no mutation sites in secondary liver cancer, indicating it has high diagnostic specificity in primary liver cancer." (PMID 35602894, 2022). "The frequency of the FOXP1/P4 peaks in the neutrophil network genes was remarkable given that the ChIPseq studies were performed in the DLD1 colon and HepG2 liver cancer cell lines, as well as in embryonic stem cells." (PMID 36756115, 2023). "For example, MRX34, a miR-34 mimic targeting forkhead box P1 (FOXP1) and BCL2, entered a multicenter phase I trial in 2013 for patients with primary liver cancer and small cell lung cancer." (PMID 32862195, 2021).
marginal zone lymphoma (4 papers, 2013 to 2020). A usually indolent mature B-cell lymphoma, arising from the marginal zone of lymphoid tissues. "FoxP1 is recurrently targeted by chromosomal translocations involving the immunoglobulin heavy chain locus in marginal zone lymphomas and DLBCL, suggesting a potential role for FoxP1 in lymphomagenesis." (PMID 23431463, 2013).
melanoma (4 papers, 2019 to 2024). A malignant, usually aggressive tumor composed of atypical, neoplastic melanocytes. "Such an effect might be related to the decreased expression of several CSC genes such as Lats1, Stat3, and Foxp1 in the ALDHhigh cells (data not shown) reported to be associated with melanoma aggressiveness." (PMID 35408953, 2022).
nasopharyngeal carcinoma (4 papers, 2017 to 2025). A carcinoma arising from the nasopharyngeal epithelium. "The development and progression of nasopharyngeal carcinoma (NPC) is associated with Epstein–Barr virus (EBV) infection and sustained inflammation, due to the inhibition of forkhead box P1 (FOXP1) tumor-suppressive activity driven by one of the 44 EBV miRNAs, EBV-miR-BART11." (PMID 38397187, 2024).
oesophageal adenocarcinoma (4 papers, 2015 to 2024). "Of all 88 included variants, we found the most significantly EAC-associated SNPs at FOXP1, which were also genome-wide significantly associated with EAC/Barrett’s esophagus in the BEACON study." (PMID 26383589, 2015). "However, further analysis showed that the expression level of FOXP1 in oesophageal squamous cell carcinoma was significantly lower than that in oesophageal adenocarcinoma, and FOXP1 expression varies in different tumour stages and grades." (PMID 38652109, 2024).
type 2 diabetes (4 papers, 2016 to 2025). "The plasma level of miR-139-5p is associated with type 2 diabetes, and their up-regulation was found in the peripheral blood of hyperglycaemia patients through suppression of FoxO1 and FoxP1." (PMID 39434104, 2024). "A total of eleven of genes were differently expressed in celiac patients compared with disease controls of which CD36, CD38, FOXP1, SELL, PPARA, PPARG, AGT previously associated with type 2 diabetes and AKAP6, NTNG1 with anorexia nervosa remained significant after correction for multiple testing." (PMID 27483138, 2016). "In addition, we discovered seven other potential key transcriptional regulators of gene expression networks in type 2 diabetes: Etv1, Irx1 and Foxp1 (alpha cells); Ehf, Hhex and Tcf4 (delta cells); and Zfhx3 (macrophages)." (PMID 39508880, 2025). "CASC2 in serum and renal tissue was specifically downregulated in patients with type 2 diabetes with podocyte injury, and CASC2 upregulation suppressed proliferation, the accumulation of extracellular matrices, and oxidative stress in mesangial cells through the miR-133b/FOXP1 regulatory axis." (PMID 37511572, 2023).
Allergy (3 papers, 2021 to 2025). An allergy is an immune response or reaction to substances that are usually not harmful. "Pathways related to intracellular signalling pathway, stress response, VEGF and MTOR related, the latter showed in the last years to be related with allergy; and oxidative phosphorylation are up-regulated, like FOXP1, SERPIN family, SOD2, caspase family, PGF, CYB5B, SERP1 and SLC25A4." (PMID 34784380, 2021).
diabetic nephropathy (3 papers, 2021 to 2022). "FOXP1 is involved in the progression of diabetic nephropathy, and FOXP1 mutation is correlated with congenital anomalies of the kidney and urinary tract." (PMID 35173708, 2021). "For instance, FOXP1 overexpression inhibits high glucose-induced extracellular matrix accumulation and oxidative stress in mesangial cells during diabetic nephropathy." (PMID 35043753, 2022). "Zhang’s study concluded that CASC2 upregulation suppressed high glucose-induced proliferation, oxidative stress of human mesangial cells and extracellular matrix accumulation through miR-133b/FOXP1 regulatory pathway, suggesting that CASC2 was a novel biomarker for diabetic nephropathy treatment." (PMID 35725478, 2022).
esophageal cancer (3 papers, 2016 to 2024). A primary or metastatic malignant neoplasm involving the esophagus. "FOXP1 predicts different overall survival outcomes in different tumours, and high expression of FOXP1 in oesophageal cancer may be associated with a better prognosis." (PMID 38652109, 2024). "In accordance with our results, have shown FGFR2 are able to promote tumor development and progression in esophageal carcinoma and FOXP1, as a member of Forkhead-box (FOX) family genes, was reported to be associated with poor prognosis of multi-cancer." (PMID 27331408, 2016). "Through the analysis of TIMER database, we found that FOXP1 expression is significantly positively correlated with B cell, CD4 + T cell, and macrophage expression level in oesophageal cancer." (PMID 38652109, 2024). "In oesophageal cancer, arm‐level deletion is the main type of SCNA of FOXP1." (PMID 38652109, 2024). "Therefore, our study suggests that the reduced expression of FOXP1 in oesophageal squamous cell carcinoma may lead to downregulation of CD4+ T cells and B cells, promoting immune escape of tumour cells and progression of oesophageal cancer." (PMID 38652109, 2024).
FOXP1 syndrome (3 papers, 2021 to 2026). "Striatal dysfunction triggered by haploinsufficiency of the forkhead box protein P1 (FOXP1) gene underlies the neurodevelopmental disorder FOXP1 syndrome, which is characterized by functional deficits in locomotion, intelligence, and language." (PMID 40537021, 2026). "Genetic mutations in the transcription factor FOXP1 (forkhead box protein P1) cause an autosomal dominant neurodevelopmental disorder called FOXP1 syndrome." (PMID 41992872, 2026). "FOXP1 syndrome (FOXP1S) (OMIM #613670) is caused by FOXP1 gene deletions and mutations (nonsense, missense, and in-frame deletions)." (PMID 35103171, 2021).
invasive breast carcinoma (3 papers, 2018 to 2022). A carcinoma that infiltrates the breast parenchyma. "In conclusion, Our results suggested that BRCA patients with high transcription levels of FOXP1/2/4 had better prognosis and FOXPs was closely related to the alteration of extensive immune checkpoints in breast invasive carcinoma." (PMID 35614183, 2022). "Moreover, PRMT5 and FOXP1 expression profile in invasive breast cancer patients undergo neoadjuvant chemotherapy." (PMID 34124017, 2021).
lung disorder (3 papers, 2019 to 2023). A disease involving the lung. "Another study based on genome-wide association data suggested FOXP1 may be a novel therapeutic target for lung disorders." (PMID 37175757, 2023). "Second, our data suggest that FoxP1 may play a role in the development of lung diseases in adults caused by tobacco exposure." (PMID 36221131, 2022). "A number of these genes have reported associations with COPD or other pulmonary diseases and include; CYP2E1, HEY1, SMAD3, BARD1 and FOXP1." (PMID 31860681, 2019). "Herein, we implicate the FoxP1 gene as a potential contributor to lung disease in adults." (PMID 36221131, 2022). "To test the hypothesis that reduced FoxP1 mRNA levels potentiate tobacco-related lung diseases such as COPD and IPF, we measured levels of MMP 1, 2, 3, and IL 6 and 8, as well as cell viability in lung epithelial cells with and without FoxP1 knockdown by RNAi." (PMID 36221131, 2022). "A causal role for FoxP1 in the pathogenesis of COPD and IPF may warrant further investigation, and FoxP1 may be a novel therapeutic target for these lung disorders." (PMID 36221131, 2022). "A causal role for FoxP1 in the pathogenesis of COPD and IPF may warrant further investigation, and FoxP1 may be a potential novel therapeutic target for these lung disorders." (PMID 36221131, 2022).
myelodysplastic syndrome (3 papers, 2014 to 2025). A clonal hematopoietic disorder characterized by dysplasia and ineffective hematopoiesis in one or more of the hematopoietic cell lines. "Methylation of the FOXP1 promoter was significantly reduced in patients with AML compared to the healthy control subjects and those with myelodysplastic syndromes." (PMID 40672953, 2025). "In patient BMA9, who was referred for myelodysplastic syndrome, OGM detected a heterozygous 289 kb deletion that includes FOXP1 (ogm[GRCh37]3p13(71,086,423_71,375,386) × 1)." (PMID 38605095, 2024).
myeloproliferative neoplasm (3 papers, 2014 to 2019). A clonal hematopoietic stem cell disorder, characterized by proliferation in the bone marrow of one or more of the myeloid (i.e., granulocytic, erythroid, megakaryocytic, and mast cell) lineages. "By contrast, FOXP1 losses have been described in clear cell-type kidney cancer but also rarely in myeloproliferative neoplasms and AML with normal or complex karyotype." (PMID 29464086, 2018). "In myeloid malignancies, FOXP1 was reported as a target of deletion in both AML and in myeloproliferative neoplasms.We also report here for the first time that FOXP1 is deregulated in MDS/AML cases." (PMID 24893616, 2014).